TNF (tumor necrosis factor)
Diseases named in the same sentence as TNF in open-access papers (continued):
Sharing a sentence is not in itself a finding about the gene and the disease.
colitis (continued). "GAL administration in DSS colitis in mice induced an increased level of anti-inflammatory cytokines (IL-10) and decreased levels of pro-inflammatory mediators (TNF, IL-6, and iNOS)." (PMID 31434263, 2019). "Recent animal studies have shown that concurrent treatment with anti-TNFα and ICIs improves tumor responses and decreases colitis severity." (PMID 31439050, 2019). "In this experiment, a rat model of colitis was established to explore probiotic VSL#3 inhibiting the expression of TNF-α in rats with colitis through TLR4-NF-κB signal pathway." (PMID 31497551, 2019). "Consistently, we observed an elevation of these cytokines, including TNF-α, IL-1β, and IL-6, p-IκB, NFκB p65, p22-phox, gp91-phox, and Keap1 in colitis mice." (PMID 31827675, 2019). "In the case of TNFα, we observed an increased concentration of this pro-inflammatory cytokine also in rats from the colitis group supplemented with high molecular weight beta-glucan (CβGh+)." (PMID 31590413, 2019). "Tussilagone, a molecule able to inhibit NF-κB activation and to induce Nrf2, reduced the main markers of murine colitis induced by DSS (i.e., TNF-α and IL-6) suggesting its potential role in the treatment of colitis." (PMID 31434263, 2019). "To understand the mechanism that underlies the alleviation of DSS-induced colitis in mice after treatment with EPS-1, we examined the levels of Th1 pro-inflammatory (TNF-α, IL-6, and IFN-γ) and anti-inflammatory (IL-4 and IL-10) in colon tissues." (PMID 30708992, 2019). "It confirms that CRHR2 receptor antagonists (Astressin2B) can block the TLR4/NF-κB signaling pathway in DSS-induced colitis mice to reduce the levels of TNF-α, IL-6, and IL-1β in serum, thereby protecting the colon mucosa." (PMID 30881446, 2019). "GA attenuates experimental colitis by suppressing IL-6, IL-1β, TNF-α, IL-17 and IFN-γ production and inhibiting p65-NF-κB and IL-6/p-STAT3 (Y705) activation." (PMID 31026283, 2019). "At d5, the TNF-α concentrations were increased in the pair-fed group compared with those at d3 (t = 2.79, P = 0.014) and were significantly higher than those in the colitis and control groups (P < 0.05)." (PMID 31221091, 2019). "For patients who require anti-TNFα agents to control irEC, ICIs are generally discontinued out of concern for recurrent, potentially treatment refractory, colitis." (PMID 31439050, 2019). "While the MMP system seems to be the strongest discriminator between healthy subjects and IBD patients, we identified markers reflecting colitis activity and anti-TNF-α treatment." (PMID 31337064, 2019). "During the pro-inflammatory response of colitis among others, NF-κB drives the expression of TNF-α and IL-6." (PMID 31010141, 2019). "In a colitis rat model, the number of ulcers, pathological scale, and TNF-α, IL-1β, and IL-6 levels were reduced following treatment with KJL." (PMID 31534467, 2019). "In the experimental colitis model, activated DCs produce numerous pro-inflammatory cytokines including TNF-α, IL-1β, IL-6, and IL-12 and express high levels of co-stimulatory molecules including CD80 and CD86." (PMID 31286993, 2019). "TGP were also shown to attenuate TNBS-induced colitis in rats by decreasing up-regulated pro-inflammatory cytokines TNF-α and IL-1β, and increasing down-regulated anti-inflammatory cytokine IL-10." (PMID 31461974, 2019). "Since TNF-α is increased in colitis and endogenous HtrA2 is able to mediate necroptosis, necroptosis can still happen even when HtrA2 is not increased during DSS treatment." (PMID 31019191, 2019). "The anti-inflammatory activity of Garcinia Kola and Ocimum Gratissimum polyphenolic extracts is exerted by reducing TNF-α and pro-inflammatory cytokine production in a rat colitis experimental model." (PMID 31031748, 2019). "Conjugated linoleic acid (CLA) can ameliorate DSS colitis through the repression of TNF-α expression and NF-κB activation and the induction of PPAR-γ." (PMID 31780872, 2019).
colitis (continued). "Application of the CSF-1 and TNFα gene sets to the TCT colitis expression data revealed both differences as well as similarities in the mechanistic impact of JNJ-40346527 and anti-TNFα." (PMID 31710624, 2019). "Through several mouse models, we demonstrated that TNF neutralization ameliorated ICB-exacerbated colitis in addition to improving ICB-dependent anti-tumor efficacy." (PMID 31309173, 2019). "With regard to the pro-inflammatory cytokines IL-1β, IL-6, and TNFα, our results are consistent with the data obtained by others, who showed that the level of pro-inflammatory cytokines increases in animals with colitis induced by exogenous agents." (PMID 31590413, 2019). "Since TNF-α is a key factor in the acute phase response, its blocking by neutralizing antibodies reached a breakthrough in the management of colitis." (PMID 31010141, 2019). "TNFα has been identified as a critical regulator of cancer cell growth in murine colitis-induced colon cancer and can promote recruitment of immune suppressive immune cells." (PMID 31461847, 2019). "ProPG treatment (ProPG + DSS group) resulted in significantly lower (P < 0.05) TNFα level in comparison to the PBS + DSS colitis control group, although it was still significantly (P < 0.05) greater than the non-DSS (PBS) control." (PMID 30873029, 2019). "While boosting anti-tumor immune responses, these therapies are also responsible for the occurrence of immune-related adverse events (irAEs) with some of them, such as colitis, being treated with TNF-blocking antibodies." (PMID 31727152, 2019). "In the MetS, CRC, Colitis, and other model experiments, the increase of Fecal butyrate content will reduce the expression of TNF-α, IL-2, NF-κB, and other pro-inflammatory factors." (PMID 32038285, 2019). "Increased levels of Flii also resulted in exacerbation of both Th1 and Th2 immune responses in colitis-induced mice with significantly greater levels of TNF-α, IFN-γ, IL-5 and IL-13 being observed." (PMID 31488864, 2019). "Similar results were obtained after prophylactic TNF blockade in graft vs host xenografted mouse models with human immune cells, which showed a reduction in colitis and hepatitis." (PMID 31309173, 2019). "Anthocyanin fraction from the tubers of purple yam down-regulated TNF-α, IFN-γ, and inflammation-associated ROS-producing enzyme myeloperoxidase (MPO) in mice treated with TNBS to induce colitis." (PMID 31137777, 2019). "In accordance with these results, Novobiocin, another inhibitor of HSP90, has been shown to mitigate DSS-induced colitis and CD45RBhigh adoptive-transfer colitis in mice via reduction of secretory inflammatory cytokines such as TNF-α." (PMID 31717769, 2019). "A higher proportion of the Batch 2 ileal CD and colitis subjects received anti-TNF alpha biologics at the time of surgery than Batch 1 subjects." (PMID 30818349, 2019). "Here, we use the mucosal delivery of Lactococcus lactis carrying an anti-TNFα scFv expression plasmid on a DSS-induced colitis model in mice." (PMID 31238939, 2019). "TNF, IL-6, IL-17A, and IL-22 levels are significantly elevated in experimental colitis and UC patients." (PMID 31137777, 2019). "In conclusion, probiotic VSL#3 inhibits the expression of NF-κB and TNF-α in rats with colitis through TLR4-NF-κB signal pathway, so it is expected to be a first choice drug for the treatment of colitis." (PMID 31497551, 2019). "In patients with severe colitis, tuberculosis testing should be completed in potential preparation for the use of anti-TNF-α inhibitors for steroid-refractory colitis." (PMID 31293970, 2019). "A common feature of this acute colitis is the massive infiltration of innate immune cells that produce large amounts of pro-inflammatory mediators such as TNFα, IL-6, IL-1β, IL-23 and GMCSF." (PMID 31189465, 2019).
colitis (continued). "Male mice were found to be more prone to colitis, which was manifested by worse microscopic and stool score, colon shortening and a higher level of TNF-α in relation to DSS-treated females." (PMID 31261736, 2019). "We aimed to investigate the effect of probiotic VSL#3 on NF-κB and TNF-α in rats with colitis and the correlation with TLR4-NF-κB signal pathway." (PMID 31497551, 2019). "Increased severity of colitis was also evidenced by increased tissue levels of IL-1β and TNFα (p < 0.05) following DSS administration." (PMID 31444382, 2019). "At d3 and d5, there were significant differences in the plasma TNF-α concentrations among the three groups (F = 4.44, P = 0.025; F = 20.02, P < 0.001) that were significantly higher in the colitis and pair-fed groups than in the control group (P < 0.05) at d3." (PMID 31221091, 2019). "A previous study conducted by some investigators from our group on the DSS‐induced colitis model, demonstrated that 5 ml kefir administration once a day reduced the disease activity index, histologic colitis scores, and the increase of TNF alpha." (PMID 31572604, 2019). "In both ICB-mediated colitis and ulcerative colitis, TNF mRNA was significantly upregulated when compared to colon healthy tissue samples." (PMID 31309173, 2019). "Our previous work has investigated the protective effects of tryptanthrin on colitis, which was closely related to TNF-α/NF-κB and IL-6/STAT3 pathways." (PMID 31726738, 2019). "In a BALB/c mouse model of DSS-induced colitis, green tea polyphenols appeared to attenuate colitis by reducing the levels of TNF-α and serum amyloid A. Notably, the effects of green tea polyphenols on colitis were similar to those of sulfasalazine." (PMID 30971953, 2019). "To gain insight into the effect of MMI-0100 on the DSS-induced colitis, we assessed a series of pro-inflammatory cytokines at mRNA levels, such as TNF-α, IL-6, IL-1β, TGF-β, IFN-γ, IL-17A, COX-2 and iNOS." (PMID 31382637, 2019). "They showed that TNF-α induces colitis through ROS production by NADPH-oxidase, and these inflammatory pathways can be inhibited by apocynin." (PMID 31141554, 2019). "Secondary immune suppression for (entero)colitis, including TNFα inhibitors, were used at similar rates in both cohorts." (PMID 31699151, 2019). "The sedentary mice fed HFD with experimental colitis presented significantly higher colonic tissue content of TNF-α, IL 1β, IL-6, IL-17, INFγ, and IL-10 as compared with the respective values of these cytokines recorded in sedentary mice fed SD (p < 0.05)." (PMID 31117199, 2019). "Several animal colitis models also demonstrate the role of TNF in the pathogenesis of intestinal inflammation." (PMID 31886308, 2019). "Mice with DSS-induced colitis exhibited substantially increased expression of TNF-α, NFκB, and IκB, compared with naïve mice." (PMID 30393231, 2018). "In this study, protein levels of TNF-α and IL-1β in colons of colitis mice were markedly increased, and alpinetin (7.5, 15, 30 mg/kg) exerted obvious inhibition." (PMID 30166541, 2018). "Convergent functions of epithelial and myeloid HuR included their requirement for suppressing inflammation in chemically induced colitis and their redundancies in chronic TNF-driven IBD and microbiota control." (PMID 30532756, 2018). "In particular, it is recognized that TNF plays a pivotal role, both in humans and experimental colitis models in the production of chemoattractants for neutrophils and their activation." (PMID 30559669, 2018). "Colitis has been reported to be exacerbated by elevated levels of IL-1β and tumor necrosis factor (TNF)-α when exposed to Salmonella typhimurium." (PMID 30583538, 2018). "Pro-inflammatory cytokines TNFα and IL-1β were used in the present study to induce a colitis-like state in the human colonic mucosa and Caco-2 cells." (PMID 30127744, 2018).
colitis (continued). "Since macrophages are major producers of TNF-α and activation of TRPA1 was able to impair the expression of TNF-α in distal colon homogenates during colitis, it is likely that TRPA1 in macrophages mediated the anti-colitogenic effect." (PMID 29467763, 2018). "In fact, pro-inflammatory cytokines (TNF, IL-1β and IL-6) contributed to tissue destruction and colitis perpetuation." (PMID 30592734, 2018). "EtOH feeding or DSS-induced colitis significantly elevated mRNA for IL-1β, TNFα and IL-6 genes in ileal mucosa." (PMID 30389960, 2018). "The protein levels of two inflammatory mediators IL-6 and TNF-α were found to have changed in the group with TRYP treatment compared with the untreated colitis group." (PMID 29724065, 2018). "The results showed that the polysaccharides ameliorated the inflammatory response through lowering TNF-α, IL-1β, IL-6 and MPO activity and increased AMPK activity in Caco-2 cell, stimulated by TNF-α in colitis rats." (PMID 30096921, 2018). "We provide evidence that F. hepatica EVs can prevent DSS-induced colitis by down regulating pro-inflammatory cytokines like TNFα, IL-6, and IL17A, as well as suppressing MAPK/NF-κB signaling pathways." (PMID 29875750, 2018). "Here we further confirmed that GWT suppresses TNF-α production in intestinal mucosa with TNBS-induced colitis." (PMID 29862296, 2018). "The observed increases in the levels of defensin, TNF-α, and IL-1β, -17α, and -22 in mice with colitis relative to healthy controls were reversed by MI-2 treatment." (PMID 30249750, 2018). "In a study of experimental colitis in mice, anti-TNF drugs, such as infliximab and etanercept, attenuated inflammation induced reductions in ZO-1 and occludin." (PMID 30127744, 2018). "Their result shows Smad nuclear-interacting protein 1 as functional downstream targets of miR-301a and diminishes trinitrobenzene sulfonic acid (TNBS)-induced colitis to decrease expression of IL-17A and TNF-α in the inflamed colon." (PMID 29599779, 2018). "We conclude that TRYP improves the health condition of mice with DSS induced colitis by regulating the TNF-α/NF-κBp65 and IL-6/STAT3 signaling pathways via inhibiting the degradation of IκBα and the phosphorylation of STAT3." (PMID 29724065, 2018). "Decreased TNF-α expression was observed when VNS were performed during the acute phase of colitis in mice with colitis and CMI." (PMID 30319530, 2018). "Triptolide (TPT), an immunosuppressive compound isolated from Chinese herb Tripterygium wilfordii Hook F., was reported to inhibit TNF as well as TNFR2 expression in the colon of mouse colitis model." (PMID 29632537, 2018). "TNF signaling has been found to induce the pleiotropic pro-inflammatory effects of colitis, including the activation of effector T cells and macrophages." (PMID 30289911, 2018). "Mice engineered to lack components of the serotonergic system have revealed 5-HTs participation in gut disease: TPH1−/− mice exhibited reduced severity of chemical-induced colitis and an accompanying reduction in IL-1β, IL-6, and TNF-α." (PMID 30177522, 2018). "These mice were compared for their responses to (a) Chemically induced Colitis; (b) Colitis- associated Cancer (CAC); (c) T-cell mediated enterotoxicity; (d) Citrobacter rodentium-induced colitis; and (e) TNF-driven inflammatory bowel disease." (PMID 30532756, 2018). "In contrast to the complex pathophysiological events that occur during DSS-induced colitis, TNF-induced necroptosis is elicited by a defined trigger and represents one of the best-studied model system for necroptosis." (PMID 29560122, 2018). "Mirroring this improvement in colitis, Rag2−/−hLrh1IEC-TG animals showed a decreased inflammatory cytokine profile, with lower intestinal expression of TNFα, IL-1β, and IL-6, and a corresponding increase in the anti-inflammatory cytokine IL-10." (PMID 30305617, 2018).
colitis (continued). "In mice, mangiferin, a bioactive compound of the mango, attenuated DSS induced colitis through directly reducing the activity of mucosal TNF-α and MMP-9." (PMID 29530095, 2018). "Pro-inflammatory cytokines, such as TNF-α, IL-1β and IL-6, play important roles in colitis development." (PMID 29495327, 2018). "In the present study, DKO mice had elevated colonic production of TNF and histologic colitis scores that were restored to IL10−/− levels with systemic reconstitution of DKO mice with BMMCs." (PMID 29849494, 2018). "PathFX also identified that etanercept, an anti-TNF-alpha drug used in auto-immune disorders, would be applicable to colitis and this identification was supported by the Jung dataset." (PMID 30532240, 2018). "In a murine T-cell transfer or TNBS model of colitis, expression of IL-1β, IL-6, tumor necrosis factor alpha (TNF-α), and IL-10, which are involved in inflammation, was regulated by B. fragilis." (PMID 30429227, 2018). "In the DSS-induced colitis mouse model, B. fragilis inhibits the expression of proinflammatory cytokines IL-6 and TNF-α and enhances the anti-inflammatory IL-10 expression, and thereby ameliorates colitis symptoms." (PMID 30060606, 2018). "Next we examined the effect of GWT on TNF-α expression in mononuclear cells that are infiltrated in colonic tissues with experimental colitis." (PMID 29862296, 2018). "We found that metformin ameliorated the induction of colitis and reduced the levels of pro‐inflammatory cytokines IL‐6, TNF‐a and IL‐1β." (PMID 29148173, 2018). "Out results demonstrated that the levels of TNF-α, IL-1β, and IL-6 were markedly downregulated in the colonic LP in colitis mice with GLP treatment." (PMID 29888292, 2018). "In particular, mollugin displays efficacy against inflammatory bowel disease (IBD) in both a TNF-α-induced colon inflammation cell culture model and a DSS/TNBS-induced IBD animal model." (PMID 30110934, 2018). "Meanwhile, the level of TNFα in the pretreated-Bifico-colitis group was decreased compared to the colitis group (P < 0.05)." (PMID 29849501, 2018). "Obvious hyperemia and inflammatory cells infiltration were found in the colitis control groups accompanied with higher proinflammatory cytokines (IL-6 and TNF-α) and lower anti-inflammatory cytokines (IL-4 and IL-10)." (PMID 29785192, 2018). "In experimental models of MS, DSS induced colitis, and lung injury, Ron plays a protective role through attenuation of TNFα in the periphery and CNS." (PMID 29616029, 2018). "We found that alpinetin (30 mg/kg) showed well reduction of DAI scores, MPO activity, shortening of colon length, histological changes and levels of TNF-α as well as IL-1β in colons of colitis mice, which was restored by CH223191 (10 mg/kg)." (PMID 30166541, 2018). "Elevated TNFα, IL-6 and IL-12 levels have been reported to be reduced by Naltrexone in chemically induced mouse colitis models." (PMID 29523156, 2018). "Plasma levels of TNFα, IL-1β and IL-6 in the plasma were significantly increased by EtOH feeding and colitis." (PMID 30389960, 2018). "Consistent with previous reports, we observed that TNBS-induced colitis invariably promoted inflammation in the colon with elevated levels of IL-1β, IL-6, TNF-α and an increased expression of JAK2, STAT3, and p-STAT3." (PMID 30042683, 2018). "In fact, nicotine, also an alkaloid, was used in low dose orally in the DSS colitis model, with improvement in clinical signs and reduction in the level of TNF-α." (PMID 30205459, 2018). "The level and expression of TNF-α and IL-6 is increased in several models of colitis, including in IBD patients." (PMID 30024891, 2018). "The results indicated that the infusion of fAT-MSCs had inhibitory effects on the expression of TNF-α, IL-1β, IFN-γ, and IL-6, which are classically associated with DSS-induced colitis, in the colonic tissue." (PMID 30453939, 2018).